GOLGA8N (golgin A8 family member N)
Tractability: No criterion of Open Targets' tractability assessment is met for any kind of drug.
Gene: Protein-coding gene on chromosome 15 (32,593,456 to 32,607,310, forward strand). Ensembl gene ENSG00000232653.
Gene Ontology:
Biological process: Golgi organization
Cellular component: cis-Golgi network; Golgi cis cisterna; Golgi cisterna membrane; Golgi apparatus
Genetic constraint (gnomAD): Loss-of-function variants: 1 observed, 3.25 expected, observed/expected ratio (o/e) 0.31, 90% interval 0.11 to 1.39. That is too few expected variants to judge how well the gene tolerates losing a copy. Missense variants: 9 observed, 19.41 expected, observed/expected ratio (o/e) 0.46, 90% interval 0.28 to 0.81. Synonymous variants: 2 observed, 6.43 expected, observed/expected ratio (o/e) 0.31, 90% interval 0.13 to 0.98.
Homologues: Orthologues: chimpanzee GOLGA8S (90% identical), mouse Golga2 (44% identical), dog GOLGA2 (44% identical), tropical clawed frog golga2 (33% identical), zebrafish golga2 (30% identical), Drosophila melanogaster GM130 (22% identical), Caenorhabditis elegans golg-2 (19% identical), rat Golga2l1 (5% identical). Paralogues in human: GOLGA8O (99% identical), GOLGA8Q (99% identical), GOLGA8R (98% identical), GOLGA8M (92% identical), GOLGA8H (90% identical), GOLGA8J (90% identical), GOLGA8K (90% identical), GOLGA8T (90% identical), GOLGA8S (84% identical), GOLGA8F (80% identical), GOLGA8G (80% identical), GOLGA8A (66% identical), and 6 more.